WNT4 (Wnt family member 4)
Description:
Ligand for members of the frizzled family of seven transmembrane receptors (Probable). Plays an important role in the embryonic development of the urogenital tract and the lung. Required for normal mesenchyme to epithelium transition during embryonic kidney development. Required for the formation of early epithelial renal vesicles during kidney development (By similarity). Required for normal formation of the Mullerian duct in females, and normal levels of oocytes in the ovaries. Required for normal down-regulation of 3 beta-hydroxysteroid dehydrogenase in the ovary. Required for normal lung development and for normal patterning of trachael cartilage rings (By similarity).
Synonyms: WNT-4; SERKAL
Tractability: Antibody: its Gene Ontology location is reachable by antibodies, with high confidence; UniProt places it where antibodies can reach, with medium confidence; UniProt predicts a signal peptide or a membrane-spanning region.
Gene: Protein-coding gene on chromosome 1 (22,117,313 to 22,143,969, reverse strand). Ensembl gene ENSG00000162552.
Subcellular location: Secreted, extracellular space, extracellular matrix
Subcellular location (Human Protein Atlas): Vesicles; Predicted to be secreted
Pathways (Reactome):
Signal Transduction: Class B/2 (Secretin family receptors); Negative regulation of TCF-dependent signaling by WNT ligand antagonists; PCP/CE pathway; TCF dependent signaling in response to WNT; WNT ligand biogenesis and trafficking
Developmental Biology: Nephron development; Transcriptional regulation of testis differentiation
Gene Ontology:
Molecular function: receptor ligand activity; cytokine activity; frizzled binding; transcription corepressor activity; signaling receptor binding
Biological process: adrenal gland development; canonical Wnt signaling pathway; cellular response to transforming growth factor beta stimulus; epithelial to mesenchymal transition; female sex determination; kidney development; liver development; male gonad development; mammary gland epithelium development; negative regulation of androgen biosynthetic process; negative regulation of DNA-templated transcription; negative regulation of gene expression; negative regulation of male gonad development; negative regulation of steroid biosynthetic process; negative regulation of testicular blood vessel morphogenesis; negative regulation of testosterone biosynthetic process; non-canonical Wnt signaling pathway; paramesonephric duct development; positive regulation of aldosterone biosynthetic process; positive regulation of bone mineralization; positive regulation of collagen biosynthetic process; positive regulation of cortisol biosynthetic process; positive regulation of dermatome development; positive regulation of DNA-templated transcription; positive regulation of MAPK cascade; and 11 more
Cellular component: cytoplasm; extracellular region; cell surface; endocytic vesicle membrane; endoplasmic reticulum lumen; extracellular exosome; Golgi lumen; plasma membrane; extracellular matrix
Genetic constraint (gnomAD): Loss-of-function variants: 16 observed, 35.01 expected, observed/expected ratio (o/e) 0.46, 90% interval 0.31 to 0.69. The upper end of that interval is the gene's LOEUF score, 0.69, which puts it in group 2 of 6, group 1 being the genes least tolerant of losing a copy. Missense variants: 379 observed, 503.33 expected, observed/expected ratio (o/e) 0.75, 90% interval 0.69 to 0.82. Synonymous variants: 200 observed, 213.96 expected, observed/expected ratio (o/e) 0.93, 90% interval 0.83 to 1.05.
Homologues: Orthologues: chimpanzee WNT4 (100% identical), dog WNT4 (100% identical), macaque WNT4 (100% identical), mouse Wnt4 (99% identical), guinea pig WNT4 (92% identical), rat Wnt4 (89% identical), tropical clawed frog wnt4 (83% identical), zebrafish wnt4 (83% identical), Caenorhabditis elegans cwn-1 (47% identical), Drosophila melanogaster Wnt5 (44% identical), Caenorhabditis elegans cwn-2 (42% identical), Drosophila melanogaster Wnt10 (38% identical), and 2 more. Paralogues in human: WNT2B (48% identical), WNT3 (48% identical), WNT7B (47% identical), WNT3A (46% identical), WNT5A (46% identical), WNT1 (46% identical), WNT2 (46% identical), WNT7A (45% identical), WNT5B (45% identical), WNT6 (43% identical), WNT10A (42% identical), WNT16 (41% identical), and 6 more.
Diseases named in the same sentence as WNT4 in open-access papers:
WNT4 is named in the same sentence as 188 diseases in open-access papers, as found by Europe PMC text mining. Sharing a sentence is not in itself a finding about the gene and the disease. The quoted sentences say what the papers report.
endometriosis (58 papers, 2012 to 2026). The growth of functional endometrial tissue in anatomic sites outside the uterine body. "Germline WNT4 SNPs are linked to 10%–25% increased risk for gynecologic pathologies including endometriosis, leiomyoma, and ovarian cancer." (PMID 38112643, 2024). "Strikingly, over 20 genome-wide association studies link SNPs at the WNT4 locus to increased risk of gynecologic pathologies including endometriosis and ovarian cancer." (PMID 38112643, 2024). "The rs2235529 SNP of WNT4 is associated with the development of endometriosis in European populations; additional validation studies have replicated the association of WNT4 with endometriosis." (PMID 37626707, 2023). "SNP rs7521902 in WNT4 is significantly correlated with the pathogenesis of endometriosis, and rs2072920 in WNT4 is associated with body mass index (BMI) variations in the Han Chinese population." (PMID 36292659, 2022). "A meta-analysis reported that genes associated with endometriosis that were involved in hormone signalling (WNT4/CDC42, GREB1, ESR1, FSHB) were also associated with diagnosis of fibroids." (PMID 35514537, 2022). "This link is an interesting insight, especially given the recurrent finding of WNT4 variants in the pathogenesis of endometriosis." (PMID 34298916, 2021). "A consensus point between these two studies is the robust association between WNT4 polymorphisms and endometriosis." (PMID 34361119, 2021). "Some of these studies revealed, for instance, novel associations between endometriosis (and some specific phenotypes) with the Wnt Family Member 4 (WNT4) locus and the mitogen-activated protein kinase (MAPK)-related pathway." (PMID 32787880, 2020). "An association between endometriosis and markers located in or near WNT4 has been highlighted in a number of extensive studies on gene mapping." (PMID 32143537, 2020). "Using a sample of 7090 individuals (2594 cases and 4496 controls), the study found the marker in the region of the WNT4 gene, with the strongest association with the risk of endometriosis: the SNP rs3820282." (PMID 32143537, 2020). "Accordingly, WNT4 dysfunction is linked to a range of endocrine and gynecologic pathologies, including endometriosis, uterine fibroids, and ovarian cancer." (PMID 33053661, 2020). "Keywords included: endometriosis combined with genes, genetics, SNPs, genome-wide association study (GWAS), WNT4, VEZT, FSHB, next-generation sequencing (NGS) and epigenetics." (PMID 32143537, 2020). "SNP rs7521902 WNT4 has been repeatedly associated in the literature with greater susceptibility to endometriosis in women of different ethnicities, including British, Australian, Italian and Japanese." (PMID 32143537, 2020). "This possible ERα/WNT4 signalling is supported by the association of the same region with endometriosis, which is an oestrogen-responsive disease." (PMID 31988393, 2020). "Our UL GWAS meta-analysis indicates that genes previously associated with endometriosis and involved in hormone-signaling pathways are also associated with UL (WNT4/CDC42, GREB1, ESR1, and FSHB)." (PMID 31649266, 2019). "Five mSNPs associated with DNAm probe sites closest to GREB1, C11orf46, NR2C1, KDR and WNT4 are located within regions associated with endometriosis risk." (PMID 30871624, 2019). "The direct association of the unfavorable WNT4 allele with endometriosis has been recently demonstrated." (PMID 29937493, 2018). "Genetic differences play a significant role in risk for endometriosis; a recent meta-analysis of over 170,000 endometriosis patients and almost 200,000 controls revealed 14 genetic regions of interest, including WNT4, GREB1, IL1A, and CDKN2B." (PMID 30134794, 2018). "Studies have suggested that rs16826658 and rs3820282 polymorphisms on the WNT4 gene are associated with the pathogenesis of endometriosis in infertile women." (PMID 29750165, 2018). "Variants at the CDC4/WNT4 locus have been associated with endometriosis, BMD, bone size, and ovarian cancer." (PMID 30194396, 2018).
endometriosis (continued). "The variants we identified also associate with risk for endometriosis, and WNT4 function is critical for decidualization ofthe endometrium and subsequently implantation and establishment of pregnancy." (PMID 28877031, 2017). "HB‐EGF, COX‐2, and Wnt4 have been implicated in the progression of endometriosis, the abnormal growth of endometrial tissues outside the uterus." (PMID 28588064, 2017). "Two loci associated with both endometriosis and female infertility (WNT4 and ESR1) may share the same putative causal variant (PP >93.6%)." (PMID 40229599, 2025). "Specifically, within the Wnt protein family, evidence for WNT4’s inverse association with endometriosis is found in six endometrial cellular contexts, mSMR (positive coefficient) and uterus- and ovary-TWAS (negative coefficient); methylation suppresses gene expression." (PMID 41377979, 2025). "Two loci associated with both endometriosis and female infertility - WNT4 and ESR1 - may share the same putative causal variant (PP>93.6%, Supp." (PMID 38562841, 2024). "Likewise, WNT4, identified to likely harbour a pleiotropic variant between uterine fibroids, urinary incontinence and endometriosis, was identified in the top 1% of genes for these three traits in addition to neck/shoulder pain." (PMID 37410157, 2023). "Indeed, intergenic 7p15.2 and WNT4 risk loci show opposite directions of effect for WHRadjBMI and endometriosis, whilst the directionality is consistent for the GRB14 SNP." (PMID 37159502, 2023). "This study was based upon 1907 cases and 5292 controls and revealed an association between CDKN2B-AS1 and endometriosis, on chromosome 9p21, and a trend towards association with WNT4, a gene of the WNT-Beta catenin cascade previously directly involved in female sex determination." (PMID 34298916, 2021). "Of these, rs3820282, which may alter the estrogen-based regulation of WNT4, also associates with leiomyoma of uterus, gestational duration and endometriosis." (PMID 32184442, 2020). "For example, WNT4 plays a direct role in the decidualization response, and WNT4 risk haplotypes for endometriosis have been reported to contain an estrogen response element that may regulate its expression." (PMID 30134794, 2018). "However, both studies describe variants in loci on chromosome 1 encoding for CDC42 and WNT4 as risk factors for uterine fibroids and endometriosis and similarly report variants in loci on chromosome 6 encoding for SYNE1 and ESR1 as risk factors for both conditions." (PMID 36304022, 2021). "Furthermore, it is possible that genetic variants in WNT4 might contribute to endometriosis susceptibility through abnormal cell growth in female genital tract." (PMID 22924156, 2012). "GWASs have also demonstrated a genetic overlap between UL and breast cancer, particularly in the ER+ subtype, as well as with endometriosis, involving genes such as WNT4/CDC42, GREB1, ESR1, and follicle-stimulating hormone subunit beta (FSHB)." (PMID 38790186, 2024). "The strongest dysregulation of uterine gene expression in endometriosis was detected in the early secretory phase, whereby a significant Wnt4 dysregulation is rarely reported (but see Liang et al67., for Wnt4 decrease)." (PMID 38346980, 2024). "Genes in the 1p36.12 locus (CDC42, WNT4, and LINC00339) have been associated with endometriosis, uterine fibroids, ovarian and endometrial cancers, and asthma." (PMID 37159502, 2023). "WNT4 was further confirmed in 400 Brazilian infertile women with endometriosis, compared with 400 control fertile women." (PMID 34298916, 2021). "A higher expression of WNT4 mRNA has been demonstrated in the eutopic endometrium of women with endometriosis than in that of healthy women, along with WNT2 and DKK1." (PMID 34445738, 2021). "In terms of genes actually found, only the region of WNT4 was identified alone in common with the endometriosis GWAS, and only one SNP reached genome wide significance, rs2475335 in PRPRD." (PMID 34298916, 2021).
endometriosis (continued). "Two POP variants associate with conditions related to estrogen exposure, rs3820282 at the WNT4 locus (leiomyoma of uterus, gestational duration and endometriosis) and rs12325192 at the SALL1 locus (leiomyoma)." (PMID 32184442, 2020). "The choice of which polymorphisms were to be analysed fell to WNT4, VEZT and FSHB genes because of their hypothetical correlation with endometriosis, according to recent findings in the literature." (PMID 32143537, 2020). "In particular, a recent study investigated in a Greek population three of these SNPs: rs7521902, rs10859871 and rs11031006, mapped respectively on WNT4, VEZT and FSHB genes, highlighting a significant association with endometriosis." (PMID 32143537, 2020). "Correspondingly, later studies found COUPTFII and WNT4 expression levels decreased in both endometrial samples from women with endometriosis and endometriotic lesions." (PMID 31387263, 2019). "The top 6 genes associated with endometriosis found in our study are CDKNB2, MAPK1, WNT4, ILA, AKT1, and KRAS." (PMID 29750165, 2018). "Recently, it has been suggested that CYP17, VDR, MUC17, COX-2, WNT4, E-cadherin, CYP19, CYP17, TYK2, NFKB1, and MUC2 gene variants also contributed to endometriosis-related infertility." (PMID 28405865, 2017). "A deeper understanding of the function of Wnt4 in female sexual-duct development would help us to explain the pathophysiological mechanisms causing MRKHBL and SERKAL syndromes, endometriosis and infertility." (PMID 26721931, 2016). "Among the SNPs identified by GWASs of endometriosis, most replicated SNP is located on chromosome 1p36 in a region close to WNT4." (PMID 27055116, 2016). "In the meta-analysis for endometriosis, rs12700667 on chromosome 7 remained the sentinel SNP after imputation, but imputed SNPs at the 5′ end of WNT4 had stronger signals than the best signal from the GWAS (rs7521902) located 20 kb upstream of the WNT4." (PMID 23982303, 2014). "OBJECTIVE: Evaluation of polymorphisms (rs16826658, rs7521902, rs3820282, rs2235529) on WNT4 gene in infertile patients with endometriosis and in the control group." (PMID 35761738, 2014). "A previous study investigated the expression of genes playing decisive roles during the female reproductive tract development including WNT4 in peritoneal tissue from endometriosis cases and controls." (PMID 24676469, 2014). "Numerous researchers have found that factors such as IL-33, hypoxia, estrogen stimulation, and WNT4 may trigger EMT in endometriosis." (PMID 40757199, 2025). "Considering loci with genome-wide significance for each trait, two endometriosis loci have lower P values than expected by chance in the WHRadjBMI GWAS: intergenic 7p15.2 and WNT4, and two of the 16 WHRadjBMI loci had P < 0.01 in the endometriosis GWAS: intergenic 7p15.2 and GRB14." (PMID 37159502, 2023). "For example, the lack of significance of the SNP rs7521902 WNT4 as an endometriosis risk variant in the population of our study is largely due to a minimum allelic frequency (MAF), very low in the Sardinian population (0.0971)." (PMID 32143537, 2020). "Two sequence variants, rs3820282 at WNT4 and rs12325192 near SALL1 also associate with other traits that are strongly affected by estrogen exposure, i.e. leiomyoma (rs3820282 and rs12325192), gestational duration (rs3820282) and endometriosis (rs3820282)." (PMID 32184442, 2020). "The WNT4 and VEZT genes are the ones most consistently associated with endometriosis." (PMID 32370117, 2020). "WNT4 was shown to be expressed in the normal peritoneum, suggesting that endometriosis can arise through a reversible transformation of the epithelium cells to endometriotic cells (metaplasia) through the developmental pathways associated with the HOXA9 and CDKN1A genes." (PMID 29937493, 2018). "We found 11 loci showing nominal association (P < 1.0 × 10−6), 3 of which were established endometriosis loci (WNT4, CDKN2BAS1, ID4) and 8 had not previously been reported." (PMID 28333195, 2017).